INS (insulin)
Diseases named in the same sentence as INS in open-access papers (continued):
Sharing a sentence is not in itself a finding about the gene and the disease.
Hyperglycemia (continued). "The over administration of insulin can lead to low blood glucose (hypoglycemia), while failure to administer enough insulin can lead to high blood glucose (hyperglycemia)." (PMID 31856801, 2019). "This study shows that fully closed-loop insulin delivery can potentially provide health-care professionals with an effective and safe clinical tool to manage hyperglycaemia in patients receiving parenteral or enteral nutritional support in hospital." (PMID 30935872, 2019). "Although these thiazolidinediones (TZDs) exhibit satisfactory effects on improving insulin sensitivity and hyperglycemia, most of them have detrimental side effects." (PMID 31138783, 2019). "Neonatal diabetes mellitus (NDM) is a monogenic form of diabetes that is characterized by hyperglycemia and the need for insulin treatment within the first 6 months of life." (PMID 31366392, 2019). "The clinical importance of these in vitro outcomes requires further investigation, given that impaired insulin sensitivity/hyperinsulinemia is frequently present in combination with hyperglycemia in diabetic patients." (PMID 31949435, 2019). "Its overt manifestation marks a decline of beta cell function below a certain threshold, where hyperglycemia emerges as a consequence of both reduced glucose uptake from insulin-resistant peripheral tissues and increased hepatic glucose output." (PMID 31480306, 2019). "This is a moot point however, because current literature reports both increased and decreased insulin secretion with acute hyperglycemia." (PMID 31600232, 2019). "FG mainly represents nocturnal hepatic gluconeogenesis dependent on hepatic insulin sensitivity and 2HG mainly reflects postprandial hyperglycemia." (PMID 31684945, 2019). "There has been an impetus for using insulin to treat the hyperglycemia frequently seen in severely ill patients in emergency rooms and intensive care units (ICUs)." (PMID 30972338, 2019). "Insulin transport to the CNS is reduced in high-fat diet-induced obesity and suppressed by hyperglycemia." (PMID 31474827, 2019). "A combination of intensive insulin treatment and ALA showed efficacy in normalizing hyperglycemia, relieving oxidative stress, and improving the beta-cell function and insulin sensitivity." (PMID 32184879, 2019). "Our findings are broadly consistent with the report that chronic glucose infusion in rats leads to moderate hyperglycemia (∼15 mM) and hyperglucagonemia, despite stimulation of insulin secretion." (PMID 30415925, 2019). "This is a retrospective audit of all patients treated with insulin for hyperglycaemia (BGL > 10 mmol/L) prior to FDG PET/CT at the Peter MacCallum Cancer Centre over a 2-year period." (PMID 30737563, 2019). "INSC93S transgenic pigs revealed impaired glucose tolerance (IGT), reduced insulin secretion and mild fasting hyperglycemia." (PMID 31308048, 2019). "Astaxanthin accumulated in skeletal muscle and was shown to reduce hyperglycemia and ameliorate insulin secretion and sensitivity by improvement of glucose metabolism and β-cell dysfunction by GLUT4 regulation." (PMID 31814873, 2019). "In this population we have already shown by use of an non-physiologic intravenous glucose tolerance test a significant improvement in hyperglycemia and a significant increase in insulin levels, which was expected as liraglutide is an insulin secretagogue." (PMID 31164926, 2019). "The pathophysiology of hyperglycaemia appears to be due to a combination of insulin and incretin suppressive effects of PAS-LAR." (PMID 31939490, 2019). "It has been demonstrated that Mesenchymal Stem Cell (MSCs) have the ability to differentiate into insulin-producing cells and secrete insulin in response to glucose and reverse the hyperglycemia in diabetic mice." (PMID 30800241, 2019). "They reported that NLRX1-deficient mice were partially protected from the development of the diet-induced hyperglycemia based on fasting glucose and insulin levels, as well as glucose tolerance." (PMID 30908533, 2019).
Hyperglycemia (continued). "Clinical trials of inhibitors that block PI3Kα commonly reported hyperglycemia as the major side effect, which is unsurprising considering the critical involvement of PI3Kα in insulin signaling." (PMID 31790629, 2019). "In the case of liver disease, hepatic IR is a consequence of an impairment on the insulin signaling pathway and glucose uptake, which leads to decreased glycogenesis and hyperglycemia." (PMID 31430977, 2019). "Tacrolimus has been reported to inhibit hyperglycemia-stimulating insulin gene expression with an inhibition rate of up to 70%." (PMID 29166433, 2019). "The resulting deficiency in endogenous insulin secretion manifests in chronic hyperglycemia with the sequential need for a lifelong reliance on exogenous insulin therapy." (PMID 31336832, 2019). "Once maternal insulin sensitivity starts to decline, typically around 18–20 weeks’ gestation, the challenge is to minimise postprandial hyperglycaemia." (PMID 31161344, 2019). "The pharmacologic management of hyperglycaemia hinges on the use of sulphonylureas, metformin and insulin." (PMID 31360518, 2019). "This medication promotes hyperglycemia which stimulates potassium channels and inhibits insulin release." (PMID 31453022, 2019). "That is, acute hyperglycemia has been shown to attenuate endothelium-dependent vasodilation, insulin secretion in addition to promoting the release of inflammatory proteins." (PMID 31382355, 2019). "The main reason for insulin infusion initiation was significant hyperglycaemia with oral antidiabetic drugs or subcutaneous insulin injections." (PMID 30689675, 2019). "Epidemiological studies have reported that dexamethasone treatment is associated with reduced birth weight in infants, even after correcting for weeks of gestation, and exhibited hypertension and greater subsequent administration of insulin for hyperglycemia." (PMID 30792693, 2019). "Briefly, serum L-carnitine level was positively correlated with serum TG level, serum insulin level, IR in males with normal fasting glucose levels and positively correlated with only serum TG level in those with hyperglycemia." (PMID 30972022, 2019). "The present study was conducted to investigate the effects of AHG on hyperglycemia in the liver of insulin resistant mice induced by a high-fat diet (HFD) for 12 weeks." (PMID 31861309, 2019). "Since improvements in insulin sensitivity often occur prior to correction of hyperglycemia, it is possible that longer durations of treatment are needed to manifest changes in glucose and insulin levels." (PMID 31315689, 2019). "Complex metabolic pathways, such as hyperglycemia and abnormal insulin signaling, are involved in DCM pathogenesis." (PMID 31572181, 2019). "The effect of incretin hormones on insulin production is crucial in alleviating postprandial hyperglycaemia in normal individuals." (PMID 31592446, 2019). "Oral administration of S-methyl cysteine sulphoxide to alloxan diabetic rats for one-month period ameliorated hyperglycaemia and was similar to animals treated with glibenclamide and insulin." (PMID 31118963, 2019). "Although correlations do not prove causality, they are consistent with reversal of the glucotoxic effect of chronic hyperglycemia on tissue sensitivity to insulin and insulin secretion." (PMID 31470605, 2019). "They target multiple molecules that are involved in the regulation of several pathways, like improving β-cell proliferation, promoting insulin secretion, reducing apoptosis, and improving hyperglycemia by regulating glucose metabolism in the liver." (PMID 31480505, 2019). "The results of our study showed that CoQ10 attenuated hyperglycemia and restored the insulin secretion ability by reducing Tac-induced oxidative stress." (PMID 31142763, 2019).
Hyperglycemia (continued). "Pre-treatment of STZ-induced, diabetic, Sprague–Dawley rats with nanosystems encapsulating curcumin (nCurcumin; 50 mg/kg b.w./day) for 28 days resulted in reduced serum glucose levels and increased insulin levels, indicating reduced hyperglycemia." (PMID 31881654, 2019). "The multireceptor-ligand pasireotide more strongly suppresses insulin secretion and gut hormones and therefore hyperglycemia is observed in more than half of the patients." (PMID 31417493, 2019). "In group A, after 72 h of i.v. continuous insulin treatment (at the time euglycemia was achieved) (second examination) and after 3 months following acute hyperglycemia (third examination) 2D-STE was repeated." (PMID 31159858, 2019). "However, special cause variation refers to any hypoglycemia or hyperglycemia incidences with the underlying cause unknown to the patient and also called unpredictable (patient uncontrollable) factors such as stress, infections, insulin set failure, and others." (PMID 31042157, 2019). "In Zucker diabetic fatty (ZDF) rats, the ingestion of a cocoa-rich diet (10%) for 9 weeks attenuated hyperglycemia, improved insulin sensitivity, and increased β-cell mass and function." (PMID 30935075, 2019). "Treatment of rat pancreatic tissue with HT (50 μg/mL) attenuated the hyperglycemia-induced decline in insulin secretion." (PMID 31234300, 2019). "Of note is that the physiological synthesis of H2S inhibition in Zucker DM rats increased insulin release and reduced hyperglycemia." (PMID 31336965, 2019). "In conclusion, cacao liquor procyanidins prevent hyperglycaemia by promoting GLUT4 translocation in skeletal muscle, and both the GLP-1-activated insulin pathway and the AMPK pathway are involved in the underlying molecular mechanism." (PMID 30719284, 2019). "This study found that SCU effectively reduces the irregular shape of pancreatic islets and enhances the levels of insulin and PK activity, further confirming its capacity to mitigate the hyperglycemia burden in db/db mice." (PMID 30881587, 2019). "This is in agreement with previous studies that have shown several risk factors of ROP to be related to glucose metabolism: caloric intake, hyperglycemia, weight gain, insulin therapy, and as a consequence, IGF-1 levels." (PMID 30954975, 2019). "We look at recent advances in understanding aerobic glycolysis and possibly the action of DPP4 on incretins resulting in insulin dysregulation and suggest key metabolic pathways involved in hyperglycemia regulation." (PMID 30972338, 2019). "Increasing hyperglycemia in T2DM is associated with increasing glucose toxicity and diminished maximum capacity of the β-cells to secrete insulin." (PMID 31781045, 2019). "Five (6%) patients had hypertension requiring oral anti-hypertensive therapy and 15(19%) patients had new onset hyperglycaemia requiring treatment with an insulin infusion for a median duration of 4 days." (PMID 31770398, 2019). "Previous work from our lab as well as others have shown hyperglycemia, elevated HbA1c% and altered insulin secretion, and sensitivity in HFD/STZ-induced rodents." (PMID 31887984, 2019). "Collectively, these data suggest that statins potentiate hyperglycemia and glucose intolerance under pre-diabetic condition via specific insulin-specific molecular defects in skeletal muscles." (PMID 31217552, 2019). "Although the in vitro differentiated HLSC-ILS were immature, they responded to high glucose with insulin secretion and in vivo reversed hyperglycemia in diabetic SCID mice." (PMID 30191384, 2019). "The phenotype of MafA-deficient adult mice showed reduced expression of insulin secretion genes, fasting hyperglycemia, and impaired glucose-stimulated insulin secretion." (PMID 31208980, 2019). "Rescue genetically modified diabetic mouse model (Akita) from hyperglycemia and was able to protect destruction of pancreatic β cells resulting in increased production of insulin." (PMID 32117210, 2019).
Hyperglycemia (continued). "We examined the effects of statins on hyperglycemia, glucose tolerance, fatty acid accumulation and insulin signaling." (PMID 31217552, 2019). "Type 1 diabetes (T1D) is characterized by impairment in beta-cell mass and insulin levels, resulting in hyperglycemia and diabetic complications." (PMID 31156453, 2019). "T2DM, the most common type of diabetes mellitus, is generally characterized by chronic hyperglycaemia, hyperinsulinemia, dyslipidaemia, as well as lipotoxicity, which result in progressive deterioration of insulin secretion and insulin action." (PMID 30781611, 2019). "It is reported that administration of STZ can induce DM via reduction of the beta cells mass and subsequently insulin secretion, which are leading to prolonged hyperglycemia." (PMID 31435592, 2019). "It suppresses insulin secretion and incretin response, resulting in a higher frequency of hyperglycaemia and diabetes." (PMID 31939490, 2019). "Acute hyperglycemia increases Aβ production, and altering insulin signaling lead to changes in Aβ levels in the brain." (PMID 30845785, 2019). "These substantial cost savings were driven by relative reductions in the frequency of hyperglycemia with ketosis and basal insulin dose with degludec versus IDet." (PMID 31543973, 2019). "In this context, polyphenols are known to positively influence postprandial glycemic responses and fasting hyperglycemia, as well as acute insulin secretion and insulin sensitivity." (PMID 31277259, 2019). "In this study, constant hyperglycemia, impaired glucose tolerance, declined serum insulin levels and a significant elevation in HbA1c and HOMA-IR were observed in diabetic rats." (PMID 31708869, 2019). "As expected, obese subjects had significantly more adverse metabolic profiles including abnormal lipid profiles, hyperglycaemia and impaired insulin sensitivity." (PMID 30729676, 2019). "In T2DM mice, small-interfering RNA-mediated Cenpx knockdown decreased hyperglycemia and upregulated insulin synthesis in the pancreas." (PMID 31417608, 2019). "Inhibition of CENPX expression in zebrafish and mouse diabetic models led to the amelioration of hyperglycemia through the induction of insulin secretion." (PMID 31417608, 2019). "Conversely, continuous infusion of olanzapine (4 or 8 mg/kg/d) for 30 days with mini-pumps in female CD-1 mice led to hyperglycemia in an oral glucose tolerance test and increased serum insulin only at the highest dose used." (PMID 31671770, 2019). "HFD/STZ-induced rats showed hyperglycemia, dyslipidemia, impaired glucose tolerance, decreased insulin, and increased HbA1c and HOMA-IR." (PMID 31887984, 2019). "A large number of oral antidiabetic drugs aimed to eliminate three major metabolic disorders leading to hyperglycemia-dysfunction of β-cells, peripheral insulin resistance, excessive hepatic glucose production." (PMID 31165274, 2019). "In non-insulin-sensitive tissues and those that passively transport glucose into cells (nerve, lens, kidneys, blood vessels), persistent extracellular hyperglycaemia leads to increased intracellular glucose." (PMID 31040781, 2019). "Contrarily to the use of mixed grains formulations in hyperglycemia management, single chickpea-based meal has also been reported to lower both the glucose and insulin amount (55% reduction in PPG at 30 and 60 min while PPI at 120 min time point)." (PMID 31737676, 2019). "We have also confirmed that SRL or EVR treatment alone results in the development of hyperglycemia, accompanied by a reduction in the number of insulin granules and an increase in the expression of oxidative stress markers, in animal models." (PMID 31142763, 2019). "According to hyperglycemia classification and detection algorithm, BG alone, and BG and insulin represent the most used types of input parameters (2/5, 40%)." (PMID 31042157, 2019).
Hyperglycemia (continued). "It is characterized by hyperglycemia due to defects in insulin secretion and/or activation, resulting in abnormalities in lipid, carbohydrate, and protein metabolism." (PMID 31443712, 2019). "While pregnancy elicits an inherent, progressive insulin-resistant state, GDM is a state where the pregnant body has become sufficiently resistant to the glucose lowering effects of insulin that hyperglycemia develops." (PMID 31647034, 2019). "In fact, TNF-α levels has been shown to increase with longer duration of disease as well as hyperglycemia and to decrease with insulin and sulfonylurea treatment." (PMID 31042755, 2019). "GLUT2 combines with the glucose kinase (GK) as the glucose receptor on islet β cells and increases glucose uptake to promote insulin secretion by sensing hyperglycemia." (PMID 31447779, 2019). "Hypertonicity in insulin-treated diabetic dogs in this study developed secondary to hyperglycemia and as such likely reflects suboptimal glycemic control." (PMID 31335875, 2019). "The quantification of these variables provides useful information to individualise GLT (e.g. hypoglycaemic agents when impaired BCF is the major driver of hyperglycaemia or biguanides when insulin resistance is in the foreground)." (PMID 31382941, 2019). "Stress response has been suggested as a mechanism of hyperglycemia after TBI by the induction of catecholamines that in turn leads to a decrease in insulin secretion." (PMID 31093304, 2019). "KIRA6 treatment was able to rescue genetically modified diabetic mouse model from hyperglycemia and was able to protect destruction of pancreatic β cells resulting in increased production of insulin." (PMID 32117210, 2019). "Under normoglycaemia, FA treatments stimulated a significant increase in insulin expression, whereas under hyperglycaemia FA had a smaller effect, suggesting that prolonged hyperglycaemia can reduce insulin production." (PMID 30710421, 2019). "For the GDM group, maternal metabolic and hormonal state remained altered (e.g. hyperinsulinemia and hyperglycaemia) at the end of pregnancy as compared to controls (e.g. C-peptide, insulin and glucose plasma levels)." (PMID 31608772, 2019). "Our current results show that efferent vagal stimulation induced insulin and adrenalectomy prevented vagal control of hyperglycemia in endotoxemia." (PMID 30700738, 2019). "Administration of NaSH dose-dependently decreased serum insulin levels in the presence of aggravated hyperglycemia, indicating decreased insulin secretion by pancreatic β-cells as previously reported in in vitro studies." (PMID 30621352, 2019). "The prioritization of insulin action on adipocyte receptors leads to lower glucose uptake than to muscle receptors and consequently hyperglycemia, increased production of pancreatic insulin, and decreased body sensitivity to insulin." (PMID 31398219, 2019). "The increase in serum tonicity in the diabetic dogs was due to hyperglycemia, which persisted despite insulin therapy." (PMID 31335875, 2019). "Metformin, sulfonylureas, thiazolidinediones and basal insulins (human NPH and insulin glargine, detemir, degludec) have little effect on postprandial hyperglycemia." (PMID 30871141, 2019). "Thiazolidinediones (TZDs) effectively attempt to mimic insulin by reducing hyperglycemia even with an impaired insulin tolerance." (PMID 31781665, 2019). "These substantial cost savings were driven by the relative reductions in the frequency of hyperglycemia with ketosis and the basal insulin dose with degludec versus IDet." (PMID 31543973, 2019). "Many of them have poorly controlled hyperglycaemia despite therapy with OADs and insulin and carry excess cardiovascular risks." (PMID 30682116, 2019). "As the onset of the early metabolic alterations (insulin tolerance and hyperglycaemia) is asymptomatic, vascular diabetic complications are often revealed at the moment of T2DM diagnosis." (PMID 31083443, 2019).